FOXL1 (forkhead box L1)
Description:
Transcription factor required for proper proliferation and differentiation in the gastrointestinal epithelium. Target gene of the hedgehog (Hh) signaling pathway via GLI2 and GLI3 transcription factors (By similarity).
Synonyms: FKHL11; FREAC7; FKH6; OTSC11
Tractability: No criterion of Open Targets' tractability assessment is met for any kind of drug.
Gene: Protein-coding gene on chromosome 16 (86,576,340 to 86,583,478, forward strand). Ensembl gene ENSG00000176678.
Subcellular location: Nucleus
Gene Ontology:
Molecular function: DNA binding; sequence-specific DNA binding; DNA binding, bending; DNA-binding transcription factor activity; DNA-binding transcription factor activity, RNA polymerase II-specific; RNA polymerase II cis-regulatory region sequence-specific DNA binding
Biological process: heart development; anatomical structure morphogenesis; cell differentiation; proteoglycan biosynthetic process; regulation of transcription by RNA polymerase II; regulation of Wnt signaling pathway; visceral mesoderm-endoderm interaction involved in midgut development; regulation of DNA-templated transcription
Cellular component: nucleus; chromatin
Genetic constraint (gnomAD): Loss-of-function variants: 2 observed, 2.33 expected, observed/expected ratio (o/e) 0.86, 90% interval 0.33 to 1.84. That is too few expected variants to judge how well the gene tolerates losing a copy. Missense variants: 547 observed, 469.51 expected, observed/expected ratio (o/e) 1.16, 90% interval 1.09 to 1.25. Synonymous variants: 273 observed, 221.13 expected, observed/expected ratio (o/e) 1.23, 90% interval 1.12 to 1.37.
Gene-disease validity (ClinGen):
ClinGen rates the evidence that FOXL1 causes each of these diseases.
congenital heart disease (autosomal dominant): Disputed. A heart disease that is present at birth.
Homologues: Orthologues: chimpanzee FOXL1 (98% identical), dog FOXL1 (87% identical), pig FOXL1 (84% identical), mouse Foxl1 (70% identical), tropical clawed frog foxl1 (47% identical), zebrafish foxl1 (43% identical), Drosophila melanogaster FoxL1 (32% identical). Paralogues in human: FOXC2 (32% identical), FOXC1 (32% identical), FOXS1 (30% identical), FOXE3 (29% identical), FOXE1 (28% identical), FOXI3 (28% identical), FOXA2 (26% identical), FOXD3 (26% identical), FOXD4L1 (26% identical), FOXD1 (26% identical), FOXA1 (26% identical), FOXL2 (26% identical), and 29 more.
Diseases named in the same sentence as FOXL1 in open-access papers:
FOXL1 is named in the same sentence as 50 diseases in open-access papers, as found by Europe PMC text mining. Sharing a sentence is not in itself a finding about the gene and the disease. The quoted sentences say what the papers report.
breast carcinoma (9 papers, 2012 to 2024). "Overexpression of FOXL1 slows down β‐catenin, c‐Myc, and cyclin D1 expression, inhibiting breast cancer cell invasion and migration." (PMID 38717954, 2024). "FOXC2 has been implicated in triple-negative breast cancer progression and therapy resistance, while FOXL1 is reported to inhibit breast cancer cell proliferation, invasion, and migration." (PMID 31910858, 2020). "The rationale for picking Phf19 and Foxl1 was that their expression was frequently deregulated in primary human breast carcinomas." (PMID 23131872, 2012). "In another study, researchers discovered that while the specific role of FOXL1 in breast cancer remains unclear, accumulating evidence shows that it may have tumor-suppressive activities, reducing proliferation and invasion in breast cancer cells." (PMID 39656775, 2024). "In the gene regulatory network by using the NetworkAnalyst web server, we found five (two from Encode and three from Jasper such as FOXC1, GATA2, FOXL1, ZNF24 and NR2F6) potential Transcription Factors (TFs) and all of those are linked with several cancer including breast cancer." (PMID 38717954, 2024). "Moreover, FOXL1 inhibited the proliferation, invasion, and migration of breast cancer both in vitro and in vivo through blocking the Wnt/β-catenin signaling pathway." (PMID 30971290, 2019). "The top significant regulatory TFs (YY1, FOXC1, FOXL1, and MEF2A) may be responsible for the related pathways of the breast cancer cellular process of disease development." (PMID 39656775, 2024).
pancreatic cancer (7 papers, 2014 to 2025). "It has been established that FOXL1 is intricately linked to the onset and progression of glioma, renal cancer, and pancreatic cancer." (PMID 38495669, 2024). "FOXL1 is a member of the forkhead box (Fox) transcription factor family, and it is involved in the regulation of epithelial cell proliferation in the gastrointestinal tract and the inhibition of growth and invasion in human pancreatic cancer cells." (PMID 33519944, 2021). "Besides GBC, a decline in expression of FOXL1 was also observed by other researchers in pancreatic tumors." (PMID 25010679, 2014). "Forkhead box L1 (FOXL1), a member of the FOX superfamily, is involved in cancer invasion and metastasis and shows abnormal expression in various tumors such as glioma, gallbladder cancer, pancreatic cancer, gastric cancer, and renal cancer." (PMID 40165896, 2025).
lung cancer (6 papers, 2020 to 2025). A malignant neoplasm involving the lung. "Dysregulation of FOXL1 can contribute to pathological conditions, including lung cancer, highlighting its importance in lung biology." (PMID 40014586, 2025). "The FOXL1 transcription factor regulates epithelial proliferation and could promote different types of cancer, including lung cancer." (PMID 36551618, 2022).
COVID-19 (4 papers, 2022 to 2023). A disease caused by infection with severe acute respiratory syndrome coronavirus 2. "The identified TFs, such as FOXC1, GATA2, YY1, FOXL1, FOXO3, STAT1 and STAT3, are associated with COVID-19." (PMID 37261353, 2023). "A recent study about the genomics of COVID-19 showed that TFs like FOXC1, GATA2, YY1, FOXL1, and NFKB1 regulated the inflammatory network in SARS-CoV-2 infections." (PMID 35747501, 2022).
gallbladder cancer (4 papers, 2014 to 2025). "It has been proved that upregulation of FOXL1 inhibits cell proliferation in vitro and tumorigenicity in vivo and stimulates the apoptosis in gallbladder cancer." (PMID 32293494, 2020). "Furthermore, upregulation of FOXL1 greatly inhibits cell proliferation, migration, and invasion in vitro, and tumorigenicity of gallbladder cancer in nude mice." (PMID 37305399, 2021). "FOXL1 is also demonstrated to be downregulated in gallbladder cancer tissues and cells." (PMID 32293494, 2020). "However, the regulation and function of FOXL1 in gallbladder cancer (GBC) remains unclear." (PMID 25010679, 2014).
gastric cancer (4 papers, 2016 to 2025). A primary or metastatic malignant neoplasm involving the stomach. "FOXL1 expression is downregulated in gastric cancer tissues and its expression significantly correlates with tumor stage, lymph node metastasis, and distant metastasis." (PMID 37305399, 2021). "We found that FOXL1 was upregulated in gastric cancer compared with normal tissues, indicating that FOXL1 will be a powerful driver in the progression of gastric cancer." (PMID 27403158, 2016). "By the FOX family member such as FOXL1, hedgehog signals can induce WNT5A upregulation, which is a cancer-associated gene involved in invasion and metastasis of gastric cancer." (PMID 27403158, 2016). "Integration analysis of SNPs and gene expression profile revealed that FOXL1 regulated the most important DEGs of IRX1, SOX1, and MSX1 with risk associated SNP loci, which may serve as candidate biomarkers for diagnosis and prognosis of gastric cancer." (PMID 27403158, 2016). "Our data showed that the expression of FOXM1 was significantly reduced in PAX8-overexpressing gastric cancer cells, but FOXC2, FOXF1, and FOXL1 remained unchanged." (PMID 30021604, 2018).
hepatocellular carcinoma (3 papers, 2019 to 2021). A malignant tumor that arises from hepatocytes. "In some other cancers, Wang and colleagues showed that the EPB41L4A-AS2-miR-301a-5p-FOXL1 axis inhibits hepatocellular carcinoma development." (PMID 34131399, 2021). "Long non-coding RNA EPB41L4A-AS2 inhibits cell proliferation and migration by downregulating miR-301a-5p expression and upregulating FOXL1 expression in hepatocellular carcinoma (HCC)." (PMID 34692706, 2021).
hypoplastic left heart syndrome (2 papers, 2009 to 2023). Hypoplastic left heart syndrome (HLHS) refers to the abnormal development of the left-sided cardiac structures, resulting in obstruction to blood flow from the left ventricular outflow tract. "In contrast to the association of point mutations in FOXF1 with bowel malrotation, microdeletions of FOXF1 were associated with hypoplastic left heart syndrome and gastrointestinal atresias, probably due to haploinsufficiency for the neighboring FOXC2 and FOXL1 genes." (PMID 19500772, 2009).
osteoporosis (2 papers, 2011 to 2022). A condition of reduced bone mass, with decreased cortical thickness and a decrease in the number and size of the trabeculae of cancellous bone (but normal chemical composition), resulting in increased fracture incidence. "Recently, a mutation in the forkhead gene (FOXL1) was identified as the causative gene of autosomal dominant otosclerosis in a large Newfoundland family, and previous studies have associated this gene with osteoporosis." (PMID 35885890, 2022). "The forkhead box transcription factor FOXL1 has been identified as the causative gene in a family with autosomal dominant otosclerosis and has been reported as a candidate gene in GWAS meta-analyses for osteoporosis." (PMID 35885890, 2022). "In humans, variants in FOXL1 and FOXC2 are associated with a reduced bone mineral density (BMD) and a risk of osteoporosis." (PMID 35885890, 2022).
otosclerosis (2 papers, 2022). Formation of spongy bone in the labyrinth capsule which can progress toward the stapes (stapedial fixation) or anteriorly toward the cochlea leading to conductive, sensorineural, or mixed hearing loss. "Interestingly, the FOXL1 variant is most frequent in Europe and rarest in Africa, which may contribute to the low prevalence of otosclerosis in Africa." (PMID 34633540, 2022). "A much larger, global case series is required to evaluate the contribution of FOXL1 to both Mendelian and sporadic otosclerosis cases." (PMID 34633540, 2022). "Limitations of this study include a limited series of otosclerosis cases which precluded our ability to estimate the prevalence or penetrance of FOXL1 otosclerosis in northern Europeans." (PMID 34633540, 2022). "The in-frame deletion of five residues in the C-terminal domain of FOXL1 in otosclerosis patients occurs in the most ordered and evolutionary-conserved portion of FOXL1." (PMID 34633540, 2022). "Targeted screening of FOXL1 (rs764026385) in the unrelated otosclerosis series identified a case (PID III-1) from the Canadian province of Ontario with allele sharing, suggesting a common ancestor." (PMID 34633540, 2022). "The remaining variant, an in-frame deletion of 15bps in the transcription factor FOXL1 (NM_005250.3: c.976_990del), was both absent in 116 ethnically matched controls and co-segregated with otosclerosis in the NL family." (PMID 34633540, 2022).
pancreatic ductal adenocarcinoma (2 papers, 2020 to 2023). An infiltrating adenocarcinoma that arises from the epithelial cells of the pancreas. "FOXL1 TF is associated with pancreatic ductal adenocarcinoma in humans." (PMID 38024867, 2023). "FOXL1 is a TF whose elevated expression is associated with good outcomes in human pancreatic ductal adenocarcinoma but does not have a known association with cardiac diseases." (PMID 32196466, 2020).
cleft palate (1 paper, 2021). Cleft palate is a fissure type embryopathy that affects the soft and hard palate to varying degrees. "This comprehensive analysis revealed decreases in gene expressions associated with lung development; Foxa2, Notch1, Foxp2, Nkx2.1, and intestine development; Cdx2, Foxf2, Foxl1, and skeletal development; Hoxd12, Hoxd13, Scx, Brachyury, and cleft palate; Foxf2." (PMID 34671097, 2021).
endometriosis (1 paper, 2018). The growth of functional endometrial tissue in anatomic sites outside the uterine body. "Here, we identified four important FOX subfamily members, FOXO1, FOXC1, FOXL1 and FOXJ1, which cooperatively regulate the integrative networks in endometriosis." (PMID 29357938, 2018).
Esophageal atresia (1 paper, 2009). A developmental defect resulting in complete obliteration of the lumen of the esophagus such that the esophagus ends in a blind pouch rather than connecting to the stomach. "The lack of intestinal atresia in group 3 suggests that either FOXC2 or FOXL1 may also contribute to this phenotype in humans, despite the fact that, in mice, haploinsufficiency for Foxf1 alone is associated with esophageal atresia." (PMID 19500772, 2009).
idiopathic pulmonary fibrosis (1 paper, 2023). Idiopathic pulmonary fibrosis (IPF) is a nonneoplastic pulmonary disease that is characterized by the formation of scar tissue within the lungs in the absence of any known cause. "A previous study suggested that FOXL1 and YY1 regulate multiple functional aspects of lung fibroblasts as a key transcription factor and are involved in idiopathic pulmonary fibrosis pathogenesis." (PMID 37925496, 2023).
Langerhans cell histiocytosis (1 paper, 2023). Langerhans cell histiocytosis (LCH) is a systemic disease associated with the proliferation and accumulation (usually in granulomas) of Langerhans cells in various tissues. "These lesions have different underlying genetic alterations, pointing to the fact that nuclear irregularities can have multiple causative factors like BRAF mutations in Langerhans cell histiocytosis and FOXL1 gene mutation in ovarian granulosa cell tumor." (PMID 37394464, 2023).
leukemia (1 paper, 2022). A malignant (clonal) hematologic disorder, involving hematopoietic stem cells and characterized by the presence of primitive or atypical myeloid or lymphoid cells in the bone marrow and the blood. "In addition, FOXK2, FOXL1, FOXO1, and FOXP3 were differentially expressed in at least six subtypes of leukemia." (PMID 36292640, 2022).
lymph node metastasis (1 paper, 2014). "Low FOXL1 expression is associated with advanced TNM stage, lymph node metastasis and poorer prognosis of GBC." (PMID 25010679, 2014). "Given that the association of FOXL1 expression with clinical stage and lymph node metastasis of GBC had been demonstrated above, it is expectedly that FOXL1 may play a role in migration and invasion of GBC." (PMID 25010679, 2014).
cancer (22 papers, 2014 to 2025). A tumor composed of atypical neoplastic, often pleomorphic cells that invade other tissues. "In this study, the ARGs signature consisted of four genes (RAMP1, FOXL1, SLCO1B3, and F2RL2) that have previously been documented to be closely linked with cancer." (PMID 40165896, 2025). "The identified TFs, such as FOXC1, FOXL1, POU2F2, NFIC, NFkB1, MEF2A, GATA2, and E2F1, are mainly associated with different types of cancers and congenital disorders." (PMID 37026010, 2023). "In contrast, another group demonstrated that FoxL1 can activate the same pathway by promoting the induction of tumor necrosis factor (TNF) related apoptosis-inducing ligand (TRAIL) in cancer cells." (PMID 35743818, 2022). "Treatment with recombinant Shh resulted in significant upregulation of Hh target genes such as Gli1 and Foxl1 in BBF2H7-expressing cancer cell lines and enhanced cell growth." (PMID 25955804, 2015). "Immunohistochemical analysis showed that FOXL1 protein was mainly localized in nuclear of cancer cells and normal epithelial cells." (PMID 25010679, 2014). "FOXL1 protein was abundantly expressed in normal tissues, but was relatively less expressed in cancer tissues." (PMID 25010679, 2014). "In contrast, FOXL1 can promote apoptosis and inhibit cancer cell metastasis." (PMID 35743172, 2022). "Forkhead Box L1 (FOXL1), a transcription factor gene located in 16q24.1, was initially discovered in the mesenchyme of the gastrointestinal tract and reported to be expressed ectopically in some types of carcinomas." (PMID 37305399, 2021). "FOXL1 is located at the junction of multiple signaling pathways and plays critical roles in a variety of physiological and pathological processes, including cancer development." (PMID 25395235, 2015). "However, there are few researches on the regulation and function of FOXL1 in cancers." (PMID 25010679, 2014). "The expression of TF-protein FOXL1 (a regulator of NT5E, TP53INP1, HPGD, FN1, OAS1 and NQO1) is connected with numerous cancer." (PMID 35617355, 2022). "Considering that FOXL1 has been extensively studied as a tumor suppressor, we selected FOXC2, a recognized oncogene in multiple cancer types, for further investigation." (PMID 33869020, 2021). "FOXL1, in turn, directly up-regulates Grem1 expression to antagonize BMP signaling and promote cancer progression by suppressing differentiation of Lgr5+ stem cells while inducing epithelial proliferation." (PMID 33197448, 2021). "FOXL1 is a member of the Forkhead box (FOX) superfamily and was reported to be dysregulated in various types of cancers." (PMID 33941222, 2021). "Forkhead box L1 (FOXL1) is a member of the Forkhead box (FOX) superfamily and was reported to be dysregulated in various types of cancers." (PMID 32677948, 2020). "Forkhead box L1 (FOXL1), considered as a novel candidate tumor suppressor, suppresses proliferation and invasion in certain cancers." (PMID 25010679, 2014). "Additionally, even though we can now infer that the FOX co‐expression relationships are globally disrupted in cancer tissues, it is still unclear how the centric FOX regulators shifted from normal (FOXN3 and FOXJ2) to cancer (FOXL1 and FOXD4L)." (PMID 37401400, 2023). "By targeting the upstream determinants of mesenchymal expression, such as TGF-β and FOXL1 or by targeting the downstream drivers of BMP signaling such as GREM1 and ISLR, one may identify new approaches to prevent and treat cancer." (PMID 33197448, 2021). "FOXL1 mRNA and protein levels were decreased in cancer tissues as compared with matched nontumor tissues." (PMID 25010679, 2014). "This potential TGF-β–FOXL1–Grem1/Islr axis that modulates BMP signaling in the colon provides a novel mechanism, to our knowledge, to help understand the polarization of CAFs within the tumor microenvironment and presents a promising target for future cancer treatment." (PMID 33197448, 2021).
cancer (continued). "However, the mechanisms for downexpression of FOXL1 expression in these cancers have not been elucidated yet." (PMID 25010679, 2014).